TLR3 (toll like receptor 3)
Diseases named in the same sentence as TLR3 in open-access papers (continued):
Sharing a sentence is not in itself a finding about the gene and the disease.
Cirrhosis (8 papers, 2014 to 2024). A chronic disorder of the liver in which liver tissue becomes scarred and is partially replaced by regenerative nodules and fibrotic tissue resulting in loss of liver function. "Among the eight TLR3 polymorphisms, only two SNPs (rs5743313 and rs5743314) showed a significant association with the risk for cirrhosis in patients with HCV when compared with patients with chronic HCV infections." (PMID 28127569, 2017). "Genes activated in response to microbial components Tlr3 and Tlr4 followed a similar pattern, elevated during inflammation and cirrhosis stages compared to the HCC timepoint (all P < 0.01) in Mdr2 −/− livers." (PMID 33858327, 2021). "In this study, we found a stepwise downregulation of TLR3 in neutrophils from patients with cirrhosis to those with ACLF." (PMID 34774066, 2021). "At the cellular and molecular level, there is a growing body of evidence indicating that TLR3 plays a role in cirrhosis pathogenesis and hepatocarcinogenesis." (PMID 28127569, 2017). "Here, we investigated the influence of genetic variants within TLR3 and determined the degree of association with HCV infection and HCV-related liver damage that results in cirrhosis and HCC." (PMID 28127569, 2017). "This hypothesis had been confirmed by detecting the relationship between TLR3 expression, HBsAg expression, and cirrhosis background." (PMID 25983748, 2015). "Therefore, the strong association of three TLR3 SNPs (rs5743313, rs5743314, and rs111611328) with HCV-related end-stage liver disease progression (cirrhosis and HCC) indicates an impairment of TLR3 function in the prevention of excessive inflammation and control of liver regeneration." (PMID 28127569, 2017). "We found that the cytoplasmic expression of TLR3 in HCC is positively related to HBsAg infection and HCC with cirrhosis and promotes interstitial immunoreactive cells infiltration and cancer cells apoptosis." (PMID 25983748, 2015). "In this study, we aimed to investigate the influence of TLR3 single-nucleotide polymorphisms (SNPs) on the susceptibility to HCV infection and HCV-related cirrhosis with or without HCC in a Saudi Arabian population." (PMID 28127569, 2017). "Intratumoral TLR3 positive rate was negatively related to the serum AFP levels (χ2 = 6.2411, P = 0.012) and positively related to HBsAg infection (χ2 = 9.5477, P = 0.002) and tumor with cirrhosis background (χ2 = 26.5278, P = 0.000)." (PMID 25983748, 2015).
endometriosis (8 papers, 2008 to 2026). The growth of functional endometrial tissue in anatomic sites outside the uterine body. "Among CD4+ T cells, a markedly increased expression of all studied TLRs was observed in the endometriosis groups (p < 0.0001 for most comparisons), with the highest levels noted for TLR3 and TLR9." (PMID 40862752, 2025). "Endometriosis patients also showed significant and obvious alterations in the mRNA expression levels of other genes in the TLR3 cascade, indicating that eutopic endometrium experiences an intense inflammatory state similar to that of the ectopic endometrium." (PMID 37033937, 2023). "TLR3 expression is increased in both ectopic and eutopic endometrium of endometriosis patients, contributing to the inflammatory state and enhanced cell viability." (PMID 37446108, 2023). "Expression of TLR3/4 in the endometrium of women with endometriosis is higher than that in healthy women." (PMID 36093086, 2022). "TLR3, 9 showed significantly lower expressions in endometriosis patients compared with the control (p<0.05)." (PMID 33209739, 2020). "In endometriosis, we can observe a significant decrease in TLR3 and TLR4 mRNA levels in eutopic tissues collected during the proliferative phase, when compared to controls (P < 0.05)." (PMID 18775079, 2008). "In endometriosis, eutopic tissues revealed weaker staining for TLR3 and TLR4 proteins when compared to controls." (PMID 18775079, 2008). "We observed markedly higher expression of TLR2, TLR3, TLR4, TLR7, TLR8, and TLR9 on CD4+, CD8+, and CD19+ lymphocytes in the endometriosis group, indicating their active participation in modulating immune responses in the disease setting." (PMID 40862752, 2025). "In the case of differentiation between endometriosis phenotypes, AUC values ≥ 0.85 were obtained for CD8 + TLR3, CD4 + TLR4, and CD19 + TLR3 in the comparisons of PE vs. CC and DIE vs. CC, suggesting their importance in distinguishing these disease subtypes." (PMID 40862752, 2025). "TLR4, TLR3 and TLR2 are members of the TLR family, mostly found in samples studied for endometriosis." (PMID 37446108, 2023). "Immunohistochemical analysis of endometriotic tissues showed that TLR3, TLR4, and MYD88 were localized in endometriosis lesions." (PMID 36093086, 2022). "Accordingly, infertile women with endometriosis have a significantly higher expression of TLR1, 5, 6, 7, 8, 10 and significantly lower expression of TLR3, 9 when compared with normal women." (PMID 33209739, 2020). "TLR3, 9, INF-β genes expression was significantly lower in endometriosis than control group (p<0.05)." (PMID 33209739, 2020). "Concerning protein localization, we found TLR3 and TLR4 proteins in glandular and epithelial cells of endometriosis patients." (PMID 18775079, 2008). "Our data suggest an involvement of TLR3 and TLR4 in endometrial diseases as we demonstrated altered expression levels for both receptors in endometriosis and endometrial adenocarcinoma." (PMID 18775079, 2008). "Our data suggest an involvement of TLR3 and TLR4 in endometrial diseases as demonstrated by altered expression levels in endometriosis and endometrial cancer." (PMID 18775079, 2008). "One study also shows that TLR3 and TLR4 expression is decreased in patients with endometriosis." (PMID 32751735, 2020).
endothelial dysfunction (8 papers, 2012 to 2025). In vascular diseases, endothelial dysfunction is a systemic pathological state of the endothelium (the inner lining of blood vessels) and can be broadly defined as an imbalance between vasodilating and vasoconstricting substances produced by (or acting on) the endothelium. "Taken together, these data show that TLR3/7/8 activation causes endothelial dysfunction only during pregnancy." (PMID 22848646, 2012). "However, this might be bought at the cost of thromboembolic events, as the latter could be caused by TLR3-induced endothelial dysfunction." (PMID 36631778, 2023). "Importantly, the adoptive transfer of TLR3-stimulated ECFCs hampered reendothelialization in a model of artery injury, further confirming the role of TLR3 in endothelial dysfunction." (PMID 40047974, 2025). "Next, we examined whether TLR3/7/8 activation in mice elicits endothelial dysfunction similar to that seen in women with PE." (PMID 22848646, 2012).
enterovirus infection (8 papers, 2015 to 2020). "In this study, we presented that human IECs (FHC and HT29 cells) are susceptible to enterovirus infection to activate the innate immune signaling involved in TLR3/IFN as a compatible model." (PMID 33203755, 2020). "Studies using TLR3-deficient mice have also revealed that TLR3 plays a critical role in defending against several enterovirus infections, such as Coxsackievirus A16, Coxsackievirus B3, Coxsackievirus B4, EV-A71, and Poliovirus." (PMID 31787104, 2019). "During enterovirus infection, the viral dsRNA is recognized by TLR3, leading to triggering of downstream signaling early in the viral replication cycle." (PMID 33203755, 2020). "Taken together, these results revealed a mechanism by which host intestine elicits immune responses against enterovirus infections through activating the TLR3/IRF1/type III IFN signaling pathway." (PMID 33203755, 2020). "Mechanistic studies demonstrated that IFN-λ production is induced upon enterovirus infection through the Toll-like receptor 3/interferon regulatory factor 1 (TLR3/IRF1) signaling pathway in IECs." (PMID 33203755, 2020). "Altogether, these results revealed a distinct mechanism by which the host elicited immune responses against enterovirus infections in intestine through activating the TLR3/IRF1/type III IFN axis." (PMID 33203755, 2020). "Although STING-dependent signaling is suppressed in the most cancerous intestine cells, we reported that similar to the normal FHC cells, cancerous HT29 cells showed active innate immune response in TLR3/IRF1/IFN signaling upon enterovirus infection." (PMID 33203755, 2020). "In conclusion, the present study reveals a distinct mechanism by which the host elicits immune responses against enterovirus infections in the intestine through activating the TLR3/IRF1/type III IFN signaling pathway." (PMID 33203755, 2020). "How other dsRNA sensors beyond TLR3 are controlled in enterovirus infections remains to be investigated." (PMID 29449668, 2018). "TLR3, 7, 8, 9, and melanoma differentiation-associated protein 5 (MDA5) are utilized to detect enterovirus infections while TLR3, 7, 8, and RIG-I are utilized to detect influenza virus infections." (PMID 30147693, 2018). "Several studies provide support that TLR3 is an essential TLR in enterovirus infection." (PMID 31117206, 2019). "Furthermore, studies using human biopsies associate polymorphisms in tlr3 gene with increased incidence of enteroviral myocarditis, indicating a role for TLR3 in the resolution of enteroviral infections." (PMID 28973047, 2017). "Similarly, IFN deficiency patients, including those with TLR3 and UNC-93B deficiency, are not susceptible to OPV vaccination complications or severe enterovirus infections." (PMID 30147693, 2018). "TLR3 is expressed under basal conditions in most cells and is not typically induced by interferon (IFN) or enterovirus infection." (PMID 31117206, 2019).
esophageal cancer (8 papers, 2015 to 2025). A primary or metastatic malignant neoplasm involving the esophagus. "In esophageal cancer TLR3 was associated with invasion and lymph node metastasis, TLR4 with lymph node metastasis and TLR7 with worse histological grade." (PMID 38709790, 2024). "In breast, prostate, and esophageal carcinomas, the expression of TLR3 correlates with tumor aggressiveness and poor clinical outcomes related to TLR3’s ability to promote cancer stem cell survival, cell invasion, and inflammation." (PMID 39348939, 2024). "In contrast, the high expression of TLR3 in KIRC, ACC, MESO, esophageal carcinoma (ESCA), and uterine carcinosarcoma (UCS); FASLG in HNSC, BLCA, and STAD; RIPK3 in COAD; RIPK1 in MESO and KIRP; FAS in ACC; and FADD in THCA was associated with good survival." (PMID 35748782, 2022).
Flavivirus Infections (8 papers, 2015 to 2025). Infections with viruses of the genus FLAVIVIRUS, family FLAVIVIRIDAE. "Studies have demonstrated that TLR3 mediates flavivirus infection in the nervous system, in case of WNV and JEV infections." (PMID 32244328, 2020). "In human cells, the host responds to flavivirus infection by recognizing viral nucleic acids through several distinct PRRs including RLRs, TLR-3, 7, and 8, NLRs, and the cyclic GMP-AMP synthase/stimulator of IFN genes- (cGAS-STING-) dependent sensing pathway." (PMID 32455136, 2020). "The importance of TLR3 in the induction of an antiviral response against flavivirus infections has been demonstrated." (PMID 29038620, 2017). "While expression may differ depending on tissue type and by a specific virus, prior studies of West Nile virus (WNV) establish that RIG-I, MDA-5, as well as Toll-like receptor 3 (TLR-3) function in Ifnar1−/− mice to limit flavivirus infection." (PMID 37800949, 2023). "However, The role of TLR3 involved in Flavivirus infection is controversial." (PMID 26005441, 2015). "The TLRs of importance during flavivirus infections are TLR-7 and TLR-8, which detect ssRNA as well as TLR-3, which identifies dsRNA produced during viral replication." (PMID 32455136, 2020). "Besides the RNA sensors TLR3, RIG-I, and MDA5, the cGAS-STING axis, triggered by the presence of DNA in the cytoplasm, has also been shown to be involved in flavivirus infections." (PMID 37965539, 2023). "TLR3 therefore seems to be involved in the proinflammatory response and the physiopathology of flavivirus infections, but not or only modestly in the IFN response." (PMID 37965539, 2023).
herpesvirus infection (8 papers, 2015 to 2025). "Some reported mutations altering the susceptibility of herpes infections include those affecting Unc-93 homolog B1 (UNC)-93B, signal transducer and activator of transcription 1 (STAT1), and Toll-like receptor 3 (TLR3)." (PMID 33401749, 2021). "Herpes infection signals via TLR3 to elicit antiviral innate immune responses in host cells." (PMID 40732672, 2025). "Many studies have shown the potential antiviral function of TLR3 in herpesvirus infection." (PMID 29050325, 2017). "Especially TLR3, which mediates downstream signaling via TRIF, has been extensively investigated in the context of herpesvirus infection." (PMID 39599852, 2024). "For example, the combination of TLR3 and TLR9 agonists has been shown to significantly reduce clinical signs of canine herpesvirus infection." (PMID 39355141, 2024). "Recent studies identified a few TRIM proteins that regulate the immune responses elicited by TLR3; notably, their roles have been characterized mostly in other contexts (not herpesvirus infection)." (PMID 39599852, 2024). "Of these, TLR3, TLR7, TLR8, and TLR9 contribute to antiviral immunity: TLR3 binds to double-stranded viral RNA; TLR7 and 8 detect single-stranded RNA viruses; and TLR9, which recognizes unmethylated cytosine-guanine (CpG) motifs in bacterial genomes, can also respond to herpesvirus infection." (PMID 33101294, 2020).
lung adenocarcinoma (8 papers, 2014 to 2025). A carcinoma that arises from the lung and is characterized by the presence of malignant glandular epithelial cells. "We analyzed the impact of TLR3 expression on the prognosis of lung adenocarcinoma patients using data from the Cancer Genome Atlas (TCGA) database and four additional cohorts (GSE72094, GSE30219, GSE50081 and GSE31210)." (PMID 40406122, 2025). "This study aims to analyze the methylation regulation of TLR3 in lung adenocarcinoma (LUAD) and to explore the association of TLR3 expression with immune microenvironment." (PMID 34094905, 2021). "Histological analyses of biopsies from patients affected by lung adenocarcinoma put into straight correlation the expressions of caspase 3 and TLR3." (PMID 33147700, 2020). "Studies have shown that IFN-α and IFN-β can activate MDA5, RIG-I, and TLR3 mRNA expression in human lung adenocarcinoma epithelial cells and human umbilical vein endothelial cells." (PMID 32178353, 2020). "Therefore, this study investigates the role of TLR3 agonists in modulating the expression of PD-L1, an immune-related molecule present on the surface of lung adenocarcinoma cells, with the aim of enhancing the efficacy of sindelimab." (PMID 40406122, 2025). "It was reported that IFN-α and IFN-β treatment of a human lung adenocarcinoma epithelial cell line and human umbilical vein endothelial cells resulted in activation of MDA5, RIG-I, and TLR3 mRNA expression." (PMID 24939427, 2014). "Therefore, local administration of TLR3 agonists in NSCLC patients could lead to the re-activation of local innate immune response and apoptosis of lung adenocarcinoma cells." (PMID 32093313, 2020).
measles (8 papers, 2011 to 2025). A highly contagious viral infection caused by the measles virus. "Polymorphic variants for TLR3 rs5743305 T/A were associated with a low humoral and cellular response to measles vaccination, presenting lower levels of measles-specific antibodies and showing a lower lymphoproliferative response compared to wild type." (PMID 40831704, 2025). "Therefore, immunological dysregulation in measles is produced by uncontrolled signaling of TLR3 mediated by this polymorphism." (PMID 37510216, 2023). "Of note, the promoter polymorphism (rs5743305, -8441 A > T) in the TLR3 gene, associated with rubella virus induced GM-CSF secretion, is the same SNP suggested to be a risk factor for lower antibody and low lymphoproliferative responses to measles vaccine." (PMID 21933421, 2011). "The links between TLR3 and measles vaccination immunity are particularly intriguing because TLR3 had been found to be a main target for laboratory-adapted measles virus strains, but not for wild-type measles virus strains, in the generation of host immunity." (PMID 37510216, 2023). "Furthermore, there are strong associations between this TLR3 SNP and the differences in the downstream intracellular signaling molecules Myeloid Differentiation factor 2 (MD-2) and Myeloid Differentiation Primary Response 88 (MyD88) in both antibody and cellular responses to measles immunization." (PMID 37510216, 2023). "The TLR3 pathway can be activated by many viruses, such as influenza A (H1N1), simian immunodeficiency, and measles." (PMID 28626766, 2017).
osteoarthritis (8 papers, 2011 to 2026). A noninflammatory degenerative joint disease occurring chiefly in older persons, characterized by degeneration of the articular cartilage, hypertrophy of bone at the margins and changes in the synovial membrane. "TLR3 activation promotes joint degeneration in osteoarthrosis." (PMID 40276505, 2025). "In addition, with different concentrations of poly(I:C) stimulation, TLR3 expression of FLSs from RA patients and patients with osteoarthritis (OA) was compared." (PMID 21708001, 2011). "Activating TLR3 selectively in MSCs enhances their regenerative properties, improving integration and functionality in damaged tissues, thus promote joint degeneration in osteoarthritis.While TLR3-induced inflammation supports innate immunity, it also impacts tissue homeostasis and repair." (PMID 40276505, 2025). "In osteoarthritis, extracellular mtRNA activates protein kinase R (PKR) and toll-like receptor 3 (TLR3), promoting proinflammatory cytokines production and apoptosis, ultimately leading to chondrocyte degeneration and joint deterioration." (PMID 40959271, 2025). "Thus the inhibition of TLR3 signalling could be a possible therapeutic target for osteoarthritis." (PMID 35277480, 2022).
pulmonary hypertension (8 papers, 2020 to 2025). Increased pressure within the pulmonary circulation due to lung or heart disorder. "Emerging evidence indicates that the expression of TLR3 is significantly downregulated in pulmonary endothelial cells from patients with pulmonary arterial hypertension (PAH)." (PMID 41293166, 2025). "Evidence shows that TLR3 plays a protective role in the pathogenesis of pulmonary arterial hypertension." (PMID 41303627, 2025). "We and others have shown that TLR3 expression and signaling are important in vascular biology and pulmonary hypertension (PH)." (PMID 32850883, 2020). "Based on its role in the systemic vasculature, our group discovered reduced endothelial TLR3 expression in PAH and revealed a protective role for a TLR3 agonist in rodent models of pulmonary hypertension." (PMID 32354189, 2020). "It should also be emphasized that the study confirmed reduced expression of TLR3 in endothelial cells in cultured pulmonary artery cells (PAEC) and in lung tissue with induced pulmonary arterial hypertension." (PMID 41303627, 2025).